MDM2 (MDM2 proto-oncogene)
Diseases named in the same sentence as MDM2 in open-access papers (continued):
Sharing a sentence is not in itself a finding about the gene and the disease.
cancer (continued). "Therefore, MDM2/MDMX dual specific inhibitors can be potential cancer therapeutics." (PMID 21423613, 2011). "However, in cancers overexpressing MDM2 this feedback loop is dysregulated." (PMID 15452548, 2004). "Compared with pre-NAC cancers, post-NAC resistant tumors exhibited a significant decrease in Livin and a significant increase in MDM2." (PMID 41551910, 2026). "Our lead compound, 13 (dCDK9-010), recruits the MDM2 E3 ligase to induce proteasome-dependent degradation of CDK9 and all cyclin T isoforms across diverse cancer models." (PMID 41970231, 2026). "Results included known cancer driver genes on eccDNA were identified, such as MYC, EGFR, CCND1 and MDM2." (PMID 40478912, 2025). "A recent report presented the synergistic effect of inhibiting both MDM2 and PPM1D, showing that dual inhibition leads to a more pronounced apoptotic response in cancer cells." (PMID 40227763, 2025). "While the downregulated DEGs in the Control vs. Poly I: C treated group of Gaddi dogs showed pathways highlighting, such as in cancer with NOTCH2, MDM2, and E2F3, the pathway related to RNA metabolism was also enriched for genes such as HNRNPA3 and XPO1." (PMID 40621499, 2025).
cancer (continued). "Recent studies have highlighted the distinct cytotoxic effects of MDM2 and NQO1 inhibitors in various cancer models." (PMID 39707614, 2025). "This suggests that combined targeting of Mdm2 and RBBP6 would produce a good treatment for cancers that overexpress these molecules." (PMID 39857778, 2025). "Other cancer genes detected in focal CNV peaks included EGFR (7p11.2 amplification), MDM2 (12q15 amplification), CCND1 (11q13.3 amplification), and MLLT10 (10p12.31 amplification), which were also enriched in TETs." (PMID 41388389, 2025). "Correspondingly, various MDM2 inhibitors, including peptide-based and small-molecule types, have been incorporated into PROTAC designs and applied to multiple cancers and diseases." (PMID 40866949, 2025). "Our findings emphasized MA242’s inhibitory effects on MDM2 and NFAT1, as well as its potential impact on cancer cell metabolism." (PMID 40046748, 2025). "Ribosomal protein-mediated control of MDM2 and MDM4 has implications for how cancer cells respond to chemotherapy." (PMID 40427096, 2025). "This study investigates MDM2 amplification in HMGA2-altered pleomorphic adenoma, atypical pleomorphic adenoma, and carcinoma ex pleomorphic adenoma." (PMID 40338436, 2025). "Several small-molecule MDM2 inhibitors, such as idasanutlin (RG7388), APG-115, and AMG232, have entered clinical trials for cancer treatment." (PMID 38811536, 2024). "The combination of MDM2 and BCL2 inhibitors is also being explored in several types of cancer cells." (PMID 39144622, 2024). "Targeting the N-terminal of MDM2 has the potential to re-program epithelial-mesenchymal transition (EMT) and prevent cancer cells from migrating." (PMID 38238592, 2024).
cancer (continued). "For instance, cancer cells’ translation of VEGF, XIAP, MYCN, and Slug mRNAs can be regulated by MDM2’s C-terminal RING domain." (PMID 38263255, 2024). "The copy gain regions were located on 1q21, 3q26, 11q13, and 12q15, with 33 genes located in narrow peak regions, including the Cancer Gene Census listed genes CCND1 and MDM2, both of which are frequently amplified in an Asian CCA cohort." (PMID 38877653, 2024). "In a panel of 115 cancer cell lines SJ3149 displays a broad antiproliferative activity profile, which shows statistically significant correlation with MDM2 inhibitor Nutlin-3a." (PMID 38228616, 2024). "We highlighted cancer type-specific genetic interactors, namely NDUFB5, MDM2, TUBA1B, and WRN, which were promising targets of existing and in-development drugs." (PMID 39578878, 2024). "Combined targeting EGFR and MDM2 stabilize FBW7, as a result, accelerates prompt MCL-1 protein turnover and augments cancer cell apoptosis." (PMID 39543744, 2024). "ALRN-6924 is a first-in-class dual MDM2/MDMX inhibitor with excellent on-target activity in multiple in vitro and in vivo cancer models that has completed Phase 1 clinical testing." (PMID 37509518, 2023). "By Western blot analysis, we showed that MDM2 was slightly decreased in both parental and USP22-Ko A549 cancer cells, while USP22 was significantly upregulated by P5091 treatment, which confirms that P5091 effectively inhibited USP7 deubiquitinase activity." (PMID 37946202, 2023). "By the way, an average proportion of GAs for known oncogenes (e.g., KIT, MYC, CTNNB1, MDM2 and APC) in the same pan-cancer cohort ranges from four to 9%." (PMID 37373333, 2023). "Among them, 6 co-opted E3 ligases, such as MDM2 and KEAP1, were highly expressed in over 30 cancer types, suggesting their high potential for broad usage in multiple cancer types." (PMID 37845222, 2023). "We also analyzed the protein levels of cell apoptosis markers in cancer cells after the co-transfection of sh-UBE2J1 and pcDNA3.1/MDM2 to validate the interaction between UBE2J1 and MDM2." (PMID 36852267, 2023).
cancer (continued). "We have previously shown that PPRHs are a valuable tool for gene silencing of relevant cancer targets such as dihydrofolate reductase, survivin, BCL2, TOP1, mTOR, MDM2, and MYC." (PMID 37108234, 2023). "These include anesthetics, anti-amyloidogenics, antidiabetic, potent mineralocorticoid receptor antagonists, dual MDM2 and CDK4 inhibitors targeting glioblastoma, anti-cancer agents towards HCT-116 and MCF-7 cancer cells." (PMID 37959862, 2023). "Depending on the mechanisms of drug-resistance in cancer cells, the protection of normal cells can be achieved with inhibitors of CDK4/6, caspases, Mdm2, mTOR, and mitogenic kinases." (PMID 36913303, 2023). "In total, FISH results on both 6q15 deletions and alterations of HER2, CCND1, MYC, MDM2, PTEN, 8p21, and 9p21 were available in subsets of 921 (HER2), 1007 (CCND1), 699 (MYC), 1022 (MDM2), 980 (PTEN), 986 (8p21), and 902 (9p21) cancers." (PMID 34625909, 2022). "In IOT, the LINC00324/miR-214-5p/CDK6|CCND1|MDM2|MDM4 axis promotes cancer cell proliferation and inhibits cancer cell apoptosis." (PMID 36620587, 2022). "Most genes related to signal transduction in the cytoplasm were inactivated in the pathway of the Molecular Mechanism of Cancer; however, the gene expression of NF-κB, c-FOS, c-JUN, MDM2, AURORA-A, BBC3, BIM, and p21CIP1 was significantly increased." (PMID 35328637, 2022).
cancer (continued). "Other MDM2 inhibitors such as RG7388, MI77301, AMG232, and HLI98 are actively being investigated in preclinical studies and clinical trials for cancer." (PMID 35326742, 2022). "While some cancers acquire amplification or overexpression of PHGDH, the first and rate-limiting step in this pathway, other types of cancers activate oncogenes such as MYC, MDM2, KRAS, and NRF2, leading to increased SSP enzyme expression." (PMID 35316216, 2022). "In our study, we found that ZLM-7 treatment was able to upregulate 14-3-3 sigma expression and inhibit MDM2 expression and subsequently lead to apoptosis and cell-cycle arrest, suggesting the possible extensive use of ZLM-7 for cancer therapy." (PMID 35890172, 2022). "Molecular docking of compounds 4 and 6, the cancer-inducing agent NDEA, and the standard sorafenib was performed on the targeted proteins, namely MDM2, TNF-α, TGF-β, FAK, and IL-6." (PMID 35661799, 2022). "For example, a number of drug candidates targeting E3 ligases such as MDM2 and XIAP have entered clinical trials for treatment of multiple types of cancer." (PMID 35771886, 2022). "Frequent copy‐number aberrations were also found for important cancer genes, such as CDKN2A, KIT, MDM2, CCND1, CDK4, and PAK1, among others." (PMID 35229492, 2022).